RECQL5 (RecQ like helicase 5)
Description:
DNA helicase that plays an important role in DNA replication, transcription and repair. Probably unwinds DNA in a 3'-5' direction (Probable). Binds to the RNA polymerase II subunit POLR2A during transcription elongation and suppresses transcription-associated genomic instability. Also associates with POLR1A and enforces the stability of ribosomal DNA arrays. Plays an important role in mitotic chromosome separation after cross-over events and cell cycle progress. Mechanistically, removes RAD51 filaments protecting stalled replication forks at common fragile sites and stimulates MUS81-EME1 endonuclease leading to mitotic DNA synthesis. Required for efficient DNA repair, including repair of inter-strand cross-links. Stimulates DNA decatenation mediated by TOP2A. Prevents sister chromatid exchange and homologous recombination. A core helicase fragment (residues 11-609) binds preferentially to splayed duplex, looped and ssDNA.
Synonyms: RecQ5; FLJ90603
Tractability: Small molecule: a structure with a bound ligand is known. PROTAC: ubiquitination databases record sites on it.
Gene: Protein-coding gene on chromosome 17 (75,626,845 to 75,667,190, reverse strand). Ensembl gene ENSG00000108469.
Subcellular location: Nucleus, nucleoplasm (Isoform Beta); Nucleus; Cytoplasm (Isoform Alpha); Cytoplasm (Isoform Gamma)
Subcellular location (Human Protein Atlas): Nucleoplasm; Cytosol
Gene Ontology:
Molecular function: ATP hydrolysis activity; DNA helicase activity; helicase activity; RNA polymerase II complex binding; 3'-5' DNA helicase activity; ATP binding; catalytic activity, acting on DNA; nucleic acid binding
Biological process: chromosome separation; DNA repair; DNA replication; mitotic cell cycle; mitotic DNA-templated DNA replication; negative regulation of transcription elongation by RNA polymerase II; DNA metabolic process; DNA recombination; regulation of DNA-templated transcription
Cellular component: cytosol; nucleoplasm; nucleus; replication fork; transcription preinitiation complex; chromosome; cytoplasm
Genetic constraint (gnomAD): Loss-of-function variants: 89 observed, 103.28 expected, observed/expected ratio (o/e) 0.86, 90% interval 0.73 to 1.03. The upper end of that interval is the gene's LOEUF score, 1.03, which puts it in group 4 of 6, group 1 being the genes least tolerant of losing a copy. Missense variants: 1,232 observed, 1,292.4 expected, observed/expected ratio (o/e) 0.95, 90% interval 0.91 to 1. Synonymous variants: 552 observed, 508.93 expected, observed/expected ratio (o/e) 1.08, 90% interval 1.01 to 1.16.
Homologues: Orthologues: chimpanzee RECQL5 (99% identical), macaque RECQL5 (92% identical), dog RECQL5 (83% identical), pig RECQL5 (82% identical), guinea pig RECQL5 (81% identical), mouse Recql5 (79% identical), rat Recql5 (77% identical), rabbit RECQL5 (76% identical), tropical clawed frog recql5 (54% identical), zebrafish recql5 (45% identical), Drosophila melanogaster RecQ5 (34% identical), Caenorhabditis elegans rcq-5 (25% identical). Paralogues in human: BLM (23% identical), WRN (20% identical), RECQL (17% identical), RECQL4 (16% identical).
Diseases named in the same sentence as RECQL5 in open-access papers:
RECQL5 is named in the same sentence as 39 diseases in open-access papers, as found by Europe PMC text mining. Sharing a sentence is not in itself a finding about the gene and the disease. The quoted sentences say what the papers report.
breast carcinoma (17 papers, 2015 to 2025). "Increased RECQL5 mRNA expression was observed in breast cancer cells and associated with poor prognosis." (PMID 35782872, 2022). "Polymorphisms in RECQL5 were associated with breast cancer, osteosarcoma, and laryngeal in a Chinese population." (PMID 35782872, 2022). "It has also been proposed that variants in RECQL5 are associated with increased breast cancer risk in the Chinese population." (PMID 30610487, 2019). "Further a number of polymorphisms are identified for the RECQ helicases that can determine survivability and susceptibility to cancers and recently we demonstrated that increased expression of RECQL5 can be associated to poor prognosis in breast cancer." (PMID 27764811, 2016). "Another study indicated that RECQL5 polymorphisms are associated with an increased breast cancer risk in Chinese population." (PMID 25945795, 2015). "Although defects in RECQL5 have not been associated with human genetic disorders, mutations in RECQL5 have been associated with tumorigenesis, including breast cancer, osteosarcoma, NUT midline carcinoma, head and neck cancer, and hereditary diffuse gastric cancer." (PMID 33718381, 2021). "RECQL5 is essential for the maintenance of genomic stability, and polymorphisms in the gene have been associated with both poor prognosis in osteosarcoma and susceptibility to breast cancer." (PMID 29348827, 2017). "Consistent with findings in breast cancer increased RECQL5 mRNA was associated with poor prognosis in bladder cancer, suggesting value as a prognostic marker, perhaps with particular value in identifying high-grade tumours which are likely to progress to more serious disease." (PMID 27764811, 2016). "We identified a homozygous missense variant in RECQL5 (NM_004259.7; c.1765 C > T; p.(Arg589Trp)) in a female (UPN083) who presented with short stature (height 154 cm), microcephaly, and a thyroid- and a breast cancer at the age of 46 years." (PMID 39979679, 2025). "Investigators developed a small-molecule inhibitor, compound 4a, which is a 1,3,4-oxadiazole derivative that specifically targeted RECQL5-positive breast cancers." (PMID 35782872, 2022). "This essential regulatory role of RECQL5 is further highlighted by the observed elevated RECQL5 expression and gene amplification in urothelial carcinoma of the bladder and in breast cancers." (PMID 32523948, 2020). "Conversely, other studies showed that RECQL5 is overexpressed in breast cancer and bladder carcinoma, and that depletion of RECQL5 can significantly reduce the progression of cancer." (PMID 31897211, 2020). "Through analyzing the Cancer Genome Atlas (TCGA) breast cancer RNA‐Seq data sets, we found that RECQL5 mRNA levels were modestly elevated in two breast tumor subtypes, luminal and triple‐negative compared with normal breast tissue." (PMID 31231988, 2019). "In addition to targeting RECQL5 specifically, the compound was also designed to evade neoadjuvant/adjuvant mediated chemoresistance often encountered in breast carcinoma." (PMID 35782872, 2022). "RECQ5 (also called RECQL5) is a tumor suppressor protein and antirecombinase that has been implicated as a possible breast cancer susceptibility gene, but its precise functions have been difficult to ascertain, in part because there is no known RECQ5-associated syndrome." (PMID 33332547, 2021). "To that end, we treated T47D, an ER‐positive breast cancer cell line, with either CPT or 5‐FU to induce replication stress and measured the ability of the control and RECQL5‐depleted cells to survive." (PMID 31231988, 2019). "Having established the role of RECQL5 in combating replication stress in TNBC cells, we wondered if the helicase also is required in non‐TNBC breast cancer cells when they were challenged with replication stress." (PMID 31231988, 2019).
breast carcinoma (continued). "A small molecule which binds specifically to DNA helicase RECQL5 and stabilizes the interaction between RECQL5 and RAD51 could inhibit the proliferation of breast cancer cells in a RECQL5-dependent manner." (PMID 35855837, 2022). "Moreover, the loss of function in DNA helicase genes including RECQL, BLM, WRN, RECQL5, and BRIP1 are also known to be highly correlated with the carcinogenesis of breast cancer and the BRCAness phenotype in breast cancer." (PMID 35855837, 2022). "Breast cancer patients with high RECQL5 expression have a negative prognosis." (PMID 37626815, 2023). "However, depleting RECQL5 in T47D, a non‐TNBC breast cancer cell line did not cause any increases in the level of endogenous DNA damage, suggesting that RECQL5 is not as irreplaceable in non‐TNBC cells as in TNBC cells." (PMID 31231988, 2019).
osteosarcoma (7 papers, 2017 to 2024). A usually aggressive malignant bone-forming mesenchymal neoplasm, predominantly affecting adolescents and young adults. "RecQ Like Helicase 5 (RECQL5) rs820196 was associated with an increased risk of osteosarcoma under all genetic models." (PMID 38360742, 2024). "The pooled ORs of 12 variants in 8 genes (CTLA-4, ERCC3, IL-8, PRCKG, RECQL5, TNF-α, XRCC3, and VEGF) were significantly associated with the risk of osteosarcoma in the main analysis." (PMID 38360742, 2024). "In prior meta-analyses, associations of genetic polymorphisms in VEGF, MDM2, CTLA-4, TNF-a, TNF-b1, PRCKG, RECQL5, XRCC3, and GST with osteosarcoma susceptibility were investigated." (PMID 38360742, 2024). "Our main analysis identified significant associations with osteosarcoma for 12 variants in 8 genes: CTLA-4, ERCC3, IL-8, PRCKG, RECQL5, TNF-α, XRCC3, and VEGF." (PMID 38360742, 2024). "RECQL5 expression is also downregulated in osteosarcoma, and can inhibit proliferation and promote apoptosis of osteosarcoma cells." (PMID 31897211, 2020). "Another study demonstrated that RECQL5 acts as a tumor suppressor in osteosarcoma, and increased expression of RECQL5 can inhibit the progression of osteosarcoma." (PMID 31897211, 2020). "RECQL5 has the ability to act as a suppressor of osteosarcoma tumors and could be a promising target for osteosarcoma treatment." (PMID 37626815, 2023). "RECQL5, a gene that is downregulated in osteosarcoma tissue and cells, was inserted into human AAVS1 safe harbor using the CRISPR/Cas9 system to investigate its function in osteosarcoma progression." (PMID 33546657, 2021). "A stable RECQL5 overexpression MG63 cell line was constructed, and significant cell proliferation inhibition, cell cycle arrest and apoptosis promotion were observed, suggesting RECQL5 that is a tumor suppressor in osteosarcoma." (PMID 33546657, 2021).
colorectal cancer (6 papers, 2014 to 2023). A primary or metastatic malignant neoplasm that affects the colon or rectum. "RECQL1, WRN, and RECQL5 mRNA expression have been found to be lower in primary colorectal carcinoma (CRC) samples compared to normal colonic mucosa, while BLM and RECQL4 mRNA levels are increased." (PMID 35782872, 2022). "A study investigated whether RECQL5 plays a role in CPT resistance in colorectal carcinoma." (PMID 35782872, 2022).
urothelial bladder carcinoma (4 papers, 2016 to 2021). "Here we demonstrate that human urothelial carcinoma of the bladder (UCC) has increased expression of RECQL5 compared to normal bladder tissue and that increasing RECQL5 expression can drive proliferation of normal bladder cells and is associated with poor prognosis." (PMID 27764811, 2016).
bladder carcinoma (3 papers, 2016 to 2023). "Nevertheless, the excessive expression of RECQL5 stimulates cellular growth and contributes to the progression of bladder carcinoma." (PMID 37626815, 2023). "RECQL5β levels were increased in bladder cancer cells, while overexpression of a helicase dead RECQL5 protein or siRNA mediated depletion of RECQL5 resulted in reduced cell survival in UCC cells." (PMID 27764811, 2016). "Further, by expressing a helicase dead RECQL5 and by depleting bladder cancer cells of RECQL5 we show that inhibition of RECQL5 activity has potential as a new target for treatment of UCC." (PMID 27764811, 2016).
Bloom syndrome (2 papers, 2014 to 2023). Bloom syndrome (BSyn) is a rare chromosomal breakage syndrome characterized by a marked genetic instability associated with pre- and postnatal growth retardation, facial sun-sensitive telangiectatic erythema, increased susceptibility to infections, and predisposition to cancer. "In human cells, the RecQ helicase family comprises five DNA helicases: RECQL1 (also known as RECQL or RECQ1), Bloom syndrome (BLM), Werner syndrome (WRN), Rothmund–Thomson syndrome (RTS; also known as RECQL4) and RECQL5." (PMID 25620975, 2014).
breast tumor (2 papers, 2018 to 2019). "Further analyses are needed of the 17(q22q25) duplication, which contains 482 genes including COL1A1, SOX9, RECQL5, and was described in specific subtypes of genomic changes in breast tumor and rhabdomyosarcoma." (PMID 29494553, 2018).
colon carcinoma (2 papers, 2010 to 2020). "In summary, we found that a haplotype in RECQL5 tagged by rs4789223 or other variants in LD with this SNP is associated with colon cancer in a case control study." (PMID 27942286, 2010). "Further study of RECQL5 as a colon cancer susceptibility gene is warranted, particularly with respect to variants in linkage disequilibrium with rs4789223." (PMID 27942286, 2010). "We examined the association of two haplotype-tagging SNPs in RECQL5 and colon cancer in a population-based study of 390 colon cancer cases and 464 population controls." (PMID 27942286, 2010). "Our results in combination with emerging evidence from model systems support RECQL5 as a novel susceptibility for colon cancer, and are worthy of further replication." (PMID 27942286, 2010). "In this study, we tested the hypothesis that RECQL5 variants are associated with colon cancer in a population-based case control study." (PMID 27942286, 2010). "The rs820196 SNP in RECQL5 is a nonsynonymous coding SNP in exon 9, which results in a change from aspartic acid to glycine; rs4789223, significantly associated with increased colon cancer risk in the haplotype analysis, is mapped at intron 8 and is not coding." (PMID 27942286, 2010). "The goal of our study was to test whether RECQL5 gene variants are associated with colon cancer susceptibility." (PMID 27942286, 2010). "We hypothesized that RECQL5 is a novel candidate gene for colon cancer given the known involvement in DNA repair and homologous recombination and association of other members of this family with known cancer disorders." (PMID 27942286, 2010).
Fanconi anemia (2 papers, 2015 to 2024). Fanconi anemia (FA) is a hereditary DNA repair disorder characterized by progressive pancytopenia with bone marrow failure, variable congenital malformations and predisposition to develop hematological or solid tumors. "Factors that normally mediate replication fork stability, including members of the Fanconi anemia gene family and the helicases PIF1 and RECQL5, showed reduced accumulation at replication forks in the absence of RNF4." (PMID 38530355, 2024).
gastric cancer (2 papers, 2020 to 2023). A primary or metastatic malignant neoplasm involving the stomach. "The role of RecQ-like helicase 5 (RECQL5) in gastric cancer (GC) is unclear." (PMID 31897211, 2020).
lymphoma (2 papers, 2016 to 2022). A malignant (clonal) proliferation of B- lymphocytes or T- lymphocytes which involves the lymph nodes, bone marrow and/or extranodal sites. "Recql5-knockout mice show a predisposition to various types of cancer, including lymphoma and solid tumors, and exhibit elevated levels of SCEs, suggesting that RECQL5 is a tumor suppressor gene." (PMID 36032672, 2022).
myeloproliferative neoplasm (2 papers, 2017). A clonal hematopoietic stem cell disorder, characterized by proliferation in the bone marrow of one or more of the myeloid (i.e., granulocytic, erythroid, megakaryocytic, and mast cell) lineages. "A recent study has reported strong synthetic lethality between RECQL5 and an activating V617F mutation in the JAK2 tyrosine kinase in patients with myeloproliferative neoplasms, and it is possible that the JAK/STAT cascade may be worthy of further exploration in the context of NMC." (PMID 29348827, 2017). "Despite its general role as a tumor suppressor, a recent study identified a strong synthetic lethal relationship between RECQL5 and an activating V617F mutation in the JAK2 non-receptor tyrosine kinase, a common oncogenic lesion in patients with myeloproliferative neoplasms (MPN)." (PMID 28100692, 2017).
Rothmund-Thomson syndrome (2 papers, 2015 to 2022). "The discovery of the WRN gene has highlighted the human RecQ homologs, RecQL4 and RecQL5, and has led to the identification of Rothmund-Thomson syndrome as a RecQ disease, leading to the idea of an association between chromosomal instability and premature aging." (PMID 36292687, 2022). "We cloned RecQL4 and RecQL5 based on the expressed sequence tag (EST) sequences homologous to these three human RecQ-like genes and identified a mutation in the RecQL4 gene in a Rothmund-Thomson syndrome patient." (PMID 36292687, 2022).
chromosomal instability syndrome (1 paper, 2022). "However, even with the rapid advances in whole-exome/genome sequencing technology, mutations of the 2 remaining RecQ helicase genes (RECQL and RECQL5) have yet to be linked to an inherited chromosomal instability syndrome." (PMID 35025765, 2022).
diffuse gastric adenocarcinoma (1 paper, 2020). An adenocarcinoma arising from the stomach. "The Cho Gastric dataset indicated that expression of RECQL5 was downregulated in diffuse gastric adenocarcinoma (n=31; P=0.020), gastric adenocarcinoma (n=4; P=6.82×10−4), and gastric mixed adenocarcinoma (n=10; P=0.007) compared with that in normal gastric tissues (n=19)." (PMID 31897211, 2020). "The Chen Gastric dataset revealed low expression of RECQL5 in diffuse gastric adenocarcinoma (n=12; P=4.64×10−8), gastric intestinal type adenocarcinoma (n=63; P=2.56×10−4), gastric mixed adenocarcinoma (n=8; P=6.77×10−5) and compared with normal gastric tissues (n=26)." (PMID 31897211, 2020).
gastric intestinal type adenocarcinoma (1 paper, 2020). An adenocarcinoma of the stomach arising on a background of intestinal metaplasia. "The DErrico Gastric dataset revealed that RECQL5 was downregulated in gastric mixed adenocarcinoma (n=4; P=0.039), gastric intestinal type adenocarcinoma (n=26; P=0.029) compared with normal gastric tissues (n=31)." (PMID 31897211, 2020).
lung adenocarcinoma (1 paper, 2023). A carcinoma that arises from the lung and is characterized by the presence of malignant glandular epithelial cells. "RECQL5 is highly expressed in LUSC and lung adenocarcinoma and can serve as an NSCLC biomarker or clinical target." (PMID 38077434, 2023).
lymph node metastasis (1 paper, 2020). "Low expression of RECQL5 was associated with depth of tumor invasion, histological differentiation and TNM stage (P<0.05), but not with patient age or sex, tumor size, lymph node metastasis, venous or lymphatic invasion or distant metastasis (P>0.05)." (PMID 31897211, 2020).
non-small cell lung carcinoma (1 paper, 2022). A group of at least three distinct histological types of lung cancer, including non-small cell squamous cell carcinoma, adenocarcinoma, and large cell carcinoma. "Overexpression of RECQL5 has been found in two subtypes of non-small cell lung cancer (NSCLC), lung adenocarcinoma (LUAD) and lung squamous carcinoma (LUSC), along with NSCLC cell lines." (PMID 35782872, 2022). "This study also suggests the therapeutic implications of targeting RECQL5 in non-small cell lung cancer." (PMID 35782872, 2022).
Stroke (1 paper, 2023). Sudden impairment of blood flow to a part of the brain due to occlusion or rupture of an artery to the brain. "In summary, we identified a novel mutation (NM_004259: c.1247T>C/p.I416T) of RECQL5 in a Han-Chinese family with MI, CAD, and stroke hemiplegia by whole-exome sequencing and Sanger sequencing." (PMID 37180972, 2023). "However, the MI, CAD, and stroke clinical features can result from the increase of plasma cholesterol, which was regulated by RECQL5." (PMID 37180972, 2023).